SIRT4 (sirtuin 4)
Diseases named in the same sentence as SIRT4 in open-access papers (continued):
Sharing a sentence is not in itself a finding about the gene and the disease.
thyroid cancer (9 papers, 2014 to 2024). "Clinically, SIRT4 mRNA expression is reduced in several malignancies, including breast, colon, bladder, gastric, ovarian, and thyroid cancers, though SIRT4 loss was particularly pronounced in lung cancer patients." (PMID 25332769, 2014). "Studies showed that SIRT4 was also reported to significantly decrease in thyroid cancer and inhibit glutamine metabolism and thus inhibit cell proliferation and invasion." (PMID 35136826, 2022). "In vitro experiments showed that SIRT4 inhibited the proliferation, migration, and invasion of thyroid-cancer cells." (PMID 33585187, 2020). "Through a comprehensive meta-analysis of SIRT4 expression in human tumors, it was found that expression of SIRT4 mRNA in tissues with bladder, breast, colon, gastric, ovarian, or thyroid cancer was significantly lower than that in corresponding normal tissues." (PMID 33585187, 2020). "SIRT4 inhibited the migration and invasion of thyroid-cancer cells by inhibiting glutamine metabolism." (PMID 33585187, 2020). "Although few studies have analyzed the role of SIRT4 in tumorigenesis to date, low expression of SIRT4 is reported in many cancers such as bladder, breast, colon, stomach, ovarian, and thyroid cancer, and correlates with a worse prognosis." (PMID 30761005, 2019). "Same is the case with SIRT4 gene, where SIRT4 mRNA expression has been observed reduced in several malignancies, including breast, colon, bladder, gastric, ovarian, lung and thyroid cancers." (PMID 26785117, 2016). "Also, SIRT4 overexpression induced cell cycle arrest in G0/G1 phase in thyroid cancer." (PMID 33033517, 2020).
diabetic nephropathy (8 papers, 2021 to 2025). "Sirt4 plays an essential role in preserving mitochondrial function and has been implicated in the development of metabolic disorders, such as diabetic kidney disease." (PMID 39911234, 2024). "Furthermore, SIRT4 overexpression markedly reduced the inflammatory response, suggesting that SIRT4 plays a protective role in preventing early pathological mechanisms underlying diabetic nephropathy." (PMID 40799515, 2025). "In conclusion, this study presents a first-of-its-kind computational pipeline targeting SIRT4 for diabetic nephropathy." (PMID 41248148, 2025). "In this context, overexpression of Sirt4 protects against diabetic nephropathy by inhibiting apoptosis in a glucose-induced mouse podocyte model." (PMID 39907422, 2025). "In a report, SIRT4 expression has been mentioned to reciprocate diabetic nephropathy by reducing oxidative stress and apoptosis." (PMID 34071497, 2021). "SIRT4 activation was found to inhibit high glucose-led free radical production, inflammation, and apoptosis in podocytes and represents a therapeutic option in diabetic nephropathy." (PMID 34071497, 2021). "Initial assays could include in vitro enzymatic activity measurements to confirm inhibition of recombinant human SIRT4, followed by in vitro podocyte or proximal tubular cell models of diabetic nephropathy to assess its effects on mitochondrial function, ROS generation, and apoptosis." (PMID 41248148, 2025). "Sirtuin 4 (SIRT4) plays a critical role in regulating oxidative stress, apoptosis, and mitochondrial dysfunction in diabetic nephropathy (DN)." (PMID 41248148, 2025). "Thus, pharmacological activation of SIRT4 and SIRT6 can be regarded as therapeutic strategies in attenuating diabetic nephropathy." (PMID 34071497, 2021).
ovarian carcinoma (8 papers, 2019 to 2025). A malignant neoplasm originating from the surface ovarian epithelium. "In ovarian cancer, It seemed that increased expression of SIRT4 was associated with a better prognosis by our univariable analysis, though without reaching statistical significance." (PMID 31113446, 2019). "For the analysis of the gene expression association with their promoter DNA methylation in ovarian cancer cell lines, our results showed that SIRT4 had significantly fewer methylations than does SIRT6, but there was one cell line that had up to 0.2 correlation more than others." (PMID 34335684, 2021). "Use of an online database of Kaplan–Meier plots ascertained the prognostic value of expression of SIRT4 mRNA in patients with ovarian cancer." (PMID 33585187, 2020). "Their studies showed that exosomes from ovarian cancer cell lines carrying PANDAR increased the SIRT4/SIRT6 mRNA proportion in ovarian cancer cells by interacting with the target gene SRSF9, significantly enhancing tumor cell survival and chemotherapy resistance in vitro." (PMID 39334866, 2024). "High expression of SIRT4 mRNA indicated the poor survival of patients with ovarian cancer." (PMID 33585187, 2020). "Elevated levels of SRSF9 are associated with a negative prognosis in ovarian cancer, as SRSF9 promotes an increased transcriptional ratio of sirtuin 4 (SIRT4)/SIRT6." (PMID 40757000, 2025). "Notably, many ovarian cancer cell lines did not have any SIRT4 promoter methylation, where SIRT6 showed the opposite manner." (PMID 34335684, 2021). "In contrast to SIRT3, the roles of the other two mtSIRTs, SIRT4 and SIRT5, are not yet explored in ovarian cancer, though their dual puzzling functions as tumor suppressors and tumor promoters have been reported in other cancers." (PMID 31113446, 2019).
pancreatic ductal adenocarcinoma (8 papers, 2020 to 2026). An infiltrating adenocarcinoma that arises from the epithelial cells of the pancreas. "We found that a sirtuin (SIRT) family member, SIRT4, was significantly associated autophagy pathway in pancreatic ductal adenocarcinoma (PDAC)." (PMID 36209169, 2023). "However, in pancreatic ductal adenocarcinoma (PDAC), it has been reported that SIRT4 inhibits tumor growth and promotes autophagy." (PMID 37301821, 2023).
glioma (7 papers, 2015 to 2025). A benign or malignant brain and spinal cord tumor that arises from glial cells (astrocytes, oligodendrocytes, ependymal cells). "The downregulation of SIRT4 in glioma highlights its potential as a biomarker for diagnosis and prognosis in glioma patients." (PMID 40710366, 2025). "Results from present study showed the significant downregulation of SIRT4 in glioma patients compared to healthy controls depicting its role as a tumor suppressor." (PMID 36809279, 2023). "GDH inhibition in glioma cells, coupled to SIRT4 activation, was shown to reduce glioma proliferation and inhibit tumor growth." (PMID 27983623, 2016). "SIRT4 overexpression in the A172 glioma cell line significantly increases cell viability after treatment with kainic acid, suggesting a protective role against excitotoxicity in glioma cells." (PMID 40710366, 2025). "Results analysis showed significant down-regulation of SIRT4 (p = 0.0337), SIRT5 (p<0.0001), GDH (p = 0.0305), OGG1-2α (p = 0.0001), SOD1 (p<0.0001) and SOD2 (p<0.0001) in glioma patients compared to controls." (PMID 36809279, 2023). "Thus, the current study is designed to investigate expression level of SIRT3, SIRT4, SIRT5 and associated genes SOD1, SOD2, OGG1-2α, PARP1, GDH and HIF1α in glioma patients and to find out whether this expressional deregulation effects the risk of glioma." (PMID 36809279, 2023). "Present study was purposed to figure out the expression level of mitochondrial sirtuins (SIRT3, SIRT4, SIRT5) and related genes (GDH, OGG1-2α, SOD1, SOD2, HIF1α and PARP1) in 153 glioma tissue samples and 200 brain tissue samples from epilepsy patients (taken as controls)." (PMID 36809279, 2023). "Unlike SIRT4, which is downregulated in glioma patients, SIRT3’s upregulation indicates that different sirtuins may have distinct roles in glioma progression." (PMID 40710366, 2025).
liver fibrosis (7 papers, 2020 to 2025). "To validate the underlying mechanisms of SIRT4 action in liver fibrosis, we treated LX-2 cells with TGF-β1 to activate them in vitro." (PMID 36376267, 2022). "We further explored the downstream mechanisms underlying the effects of SIRT4 on liver fibrosis." (PMID 36376267, 2022). "The loss of SIRT4 expression in liver fibrosis prompted us to determine whether overexpression of SIRT4 can inhibit the activation of HSCs." (PMID 36376267, 2022). "In liver fibrosis, SIRT4 expression is downregulated, impairing NKs’ (natural killer cells) cell cytotoxicity against HSCs (Hematopoietic Stem Cells)." (PMID 40710366, 2025). "In conclusion, the present work showed that ferroptosis contributes to the pathogenesis of liver fibrosis in NASH with T2DM by promoting hepatocyte EMT, and that AGER1 can ameliorate liver fibrosis through inhibiting ferroptosis by regulating Sirt4." (PMID 37280194, 2023). "In conclusion, these findings suggested that SIRT4 alleviates liver fibrosis by regulating glutamine metabolism." (PMID 36376267, 2022). "The present study also indicated that SIRT4 plays an inhibitory role during liver fibrosis by regulating glutamine energy metabolism." (PMID 36376267, 2022). "We are the first to discover that the expression of SIRT4 in activated HSCs in the liver is reduced and that overexpression of SIRT4 can significantly inhibit the proliferation of HSCs and reverse liver fibrosis." (PMID 36376267, 2022). "In this study, we described the protective role played by SIRT4 in the pathogenesis of liver fibrosis." (PMID 36376267, 2022). "To explore the potential role of SIRT4 in liver fibrosis, we first compared the expression of SIRT4 in different models." (PMID 36376267, 2022). "In contrast, the expression of SIRT4 was significantly reduced compared with that in normal liver tissue in both murine liver fibrosis models and human liver samples." (PMID 36376267, 2022). "In our study, we demonstrated that the expression of SIRT4 was also markedly decreased in mouse models of liver fibrosis induced by CCl4 injection and BDL." (PMID 36376267, 2022). "In this study, we measured the expression of SIRT4 and found that it was downregulated in liver fibrosis." (PMID 36376267, 2022). "To explore the precise function of SIRT4 in the pathogenesis of liver fibrosis, we generated SIRT4-overexpressing human HSCs." (PMID 36376267, 2022). "Our study indicated that knockdown of miR‐130b‐5p can alleviate hepatic fibrosis by targeting SIRT4 via the AMPK/TGF‐β/Smad2/3 signalling pathway." (PMID 34272822, 2021). "Knockdown of miR‐130b‐5p increased SIRT4 expression and ameliorated liver fibrosis in mice transfected with antagomiR‐130b‐5p oligos." (PMID 34272822, 2021). "Further experiments revealed that miR‐130b‐5p promoted liver fibrosis, mechanistically activating HSCs and promoting its proliferation by repressing SIRT4 expression." (PMID 34272822, 2021). "All in all, these results identify that the miR‐130b‐5p/SIRT4 axis as a possible novel regulator of HSC‐mediated liver fibrosis and a potential therapeutic target." (PMID 34272822, 2021). "In conclusion, our findings demonstrated that miR‐130b‐5p promotes liver fibrosis by regulating SIRT4 via the AMPK/TGF‐β/Smad2/3 signalling pathway." (PMID 34272822, 2021). "However, our study advances our understanding of the function of SIRT4 in liver fibrosis, especially in HSCs." (PMID 36376267, 2022). "To investigate the role of SIRT4 in liver fibrosis, we overexpressed SIRT4 in LX2 cells." (PMID 36376267, 2022). "Hence, we proposed that SIRT4 alleviates liver fibrosis by regulating glutamine metabolism reprogramming." (PMID 36376267, 2022).
liver fibrosis (continued). "Interestingly, we showed that SIRT4 expression was downregulated in liver fibrosis and that SIRT4 exerted antifibrotic effects by regulating glutamine metabolism in HSCs." (PMID 36376267, 2022). "Moreover, the protein expression levels of SIRT4 were lower in the liver fibrosis sample from patients than in those of normal controls." (PMID 34272822, 2021). "A previous study showed that the overexpression of SIRT4 can prevent HFD‐induced liver fibrosis." (PMID 34272822, 2021). "The results showed that overexpression of SIRT4 inhibited liver fibrosis." (PMID 34272822, 2021). "Furthermore, antagomiR‐130b‐5p ameliorated liver fibrosis and promoted SIRT4 expression in animal models." (PMID 34272822, 2021). "Sirtuin (SIRT) is known to prevent nonalcoholic fatty liver disease (NAFLD); however, the role of SIRT4 in the progression of hepatic fibrosis remains unknown." (PMID 32365537, 2020). "Although SIRT1 plays a pivotal role in the prevention of HFD-induced liver fibrosis development, the functional role of SIRT4 in the progression of hepatic fibrosis remains unknown." (PMID 32365537, 2020). "The role of SIRT4 in liver fibrosis and the related mechanisms are unknown." (PMID 36376267, 2022). "Hence, the immunostaining results supported the inhibitory effects of SIRT4 on liver fibrosis." (PMID 36376267, 2022). "However, some studies have shown that the SIRT4/Smad4 axis plays a key role in the formation of liver fibrosis, and the upregulation of SIRT4 may reduce lipid accumulation, inflammation, and fibrosis induced by HFD." (PMID 36008973, 2022). "Recent study had been demonstrated that SIRT4 could alleviate the HFD‐induced liver fibrosis." (PMID 34272822, 2021). "However, the role of SIRT4 in liver fibrosis and the related mechanisms are unknown." (PMID 36376267, 2022). "Collectively, our study reveals that SIRT4 controls GDH enzyme activity and expression, targeting glutamine metabolism in HSCs and alleviating liver fibrosis." (PMID 36376267, 2022). "However, the role of SIRT4 in liver fibrosis remains unclear." (PMID 36376267, 2022). "However, the direct correlation between SIRT4 expression and hepatic fibrosis was unknown." (PMID 32365537, 2020). "Although SIRT4 functions as an ADP-ribosyltransferase and deacetylase, we speculate that SIRT4 may inhibit glutaminolysis in activated HSCs during liver fibrosis through a GDH-dependent pathway." (PMID 36376267, 2022).
nonalcoholic fatty liver disease (7 papers, 2014 to 2022). "Meanwhile, a study found that nonalcoholic fatty liver disease patients exhibited increased SIRT4 expression and potentially a decrease in fatty acid oxidation in the liver." (PMID 31447696, 2019). "Sirt4 expression is increased in livers of patients with non-alcoholic fatty liver disease (NAFLD)." (PMID 32373514, 2020). "A more recent study highlighted a novel mechanism that deacetylating and destabilizing MTPα, a key enzyme in β-oxidation by SIRT4 may contribute to the pathogenesis of Nonalcoholic fatty liver disease (NAFLD)." (PMID 27916001, 2016). "The present study shows low circulating levels of SIRT4 in obese patients with nonalcoholic fatty liver disease mirroring its reduced mitochondrial expression in an attempt to increase the fat oxidative capacity and then the mitochondrial function in liver and in muscle." (PMID 25045415, 2014). "Because fatty acid oxidation is closely related to the production of mitochondrial ROS, SIRT4 modulation of fatty acid metabolism can reduce high circulating levels of free fatty acids but unfortunately increase ROS production in obese patients with nonalcoholic fatty liver disease." (PMID 31447696, 2019). "In non-alcoholic fatty liver disease (NAFLD), SIRT4 deacetylates and destabilizes mitochondrial trifunctional protein-alpha (MTPα), thereby affecting fatty acid β-oxidation." (PMID 36760798, 2022).
type 2 diabetes (7 papers, 2014 to 2025). "On the other hand, in advanced type 2 diabetes with its complications, an increase of SIRT4 in peripheral blood mononuclear cells was observed, which was explained by a feedback mechanism increasing SIRT4 levels." (PMID 40725501, 2025). "Our western blotting results showed that STZ-treatment markedly downregulated SIRT4 expression, which was consistent with the results of previous studies in a mouse model of type-2 diabetes and insulin-resistant rats." (PMID 35956936, 2022). "Taken together, these results demonstrate that SIRT4 inhibition increases the fat oxidative capacity in the liver and mitochondrial function in muscle, which might provide therapeutic benefits for diseases associated with ectopic lipid storage, such as type 2 diabetes." (PMID 27104517, 2016). "In contrast, our data did not confirm this expectation, although it is in line with the low SIRT4 expression in peripheral blood leukocytes of patients with type 2 diabetes mellitus." (PMID 25045415, 2014). "It has been recently observed that SIRT4 inhibition increases mitochondrial function and fatty acid oxidation in liver and muscle cells, suggesting therapeutic benefits for metabolic diseases such as type 2 diabetes." (PMID 29786646, 2018). "A previous report revealed a relationship between Sirt4 and the development of DKD: Sirt4 expression was decreased in a mouse model of type 2 diabetes, and HG-induced podocytes exhibited markedly suppressed proliferative capacity and increased apoptosis." (PMID 34439446, 2021).
colon carcinoma (6 papers, 2019 to 2025). "Since recent evidence suggests that SIRT4 inhibits autophagy in colon cancer cells, we hypothesized that SIRT4 may regulate BLCA growth and survival by regulating autophagy." (PMID 37301821, 2023). "The research found that the inhibition of SIRT4 would activate GLS, thereby initiating AKT activation, suggesting that GLS might influence the proliferation, migration, and invasion of colon cancer cells through the AKT/GSK3β/CyclinD1 pathway under the regulation of SIRT4." (PMID 41152153, 2025). "Our recent study showed that SIRT4 enhances the sensitivity of colon cancer cells to 5-FU by inhibiting autophagy (not published)." (PMID 37301821, 2023).
lung carcinoma (6 papers, 2014 to 2024). "Carrying out IHC analyses on 133 lung-cancer tissues, it was found that SIRT4 expression was decreased dramatically in 52.6% of lung-cancer tissues." (PMID 33585187, 2020). "Upregulation of SIRT4 expression inhibited the proliferation, invasion and migration of lung-cancer cell lines." (PMID 33585187, 2020). "SIRT4 inhibited the migration and invasion of lung-cancer cells by inhibiting the mitochondrial fission induced by Drp1." (PMID 33585187, 2020). "In vivo experiments also showed that SIRT4 overexpression delayed tumor growth notably, and that SIRT4 expression was negatively correlated with p-Drp1 expression in lung-cancer samples." (PMID 33585187, 2020). "Subsequently, using the K‐M plotter, we investigated the relationship between the expression of SIRTs and prognostic survival rate in lung cancer patients and found that the high expression of SIRT1, SIRT3 and SIRT4 was associated with better prognosis, respectively." (PMID 39501597, 2024).